PLK2 (polo like kinase 2)
Diseases named in the same sentence as PLK2 in open-access papers (continued):
Sharing a sentence is not in itself a finding about the gene and the disease.
Alzheimer disease (3 papers, 2016 to 2023). A progressive, neurodegenerative disease characterized by loss of function and death of nerve cells in several areas of the brain leading to loss of cognitive function such as memory and language. "Increased expression of PLK2 was observed in the brains of patients with Alzheimer's disease and LB disease." (PMID 27032368, 2016). "One is PLK2, a kinase that is shown to promote α-syn phosphorylation at serine 129 and is highly expressed in the brain of patients with Alzheimer's disease and LB disease." (PMID 27032368, 2016). "They discovered that PLK2 activity inhibition alters APP and tau pathology and enhances synaptic content in a sex-dependent manner in Alzheimer’s dementia, suggesting that it may contribute to the aetiology of the illness." (PMID 36982508, 2023).
diabetes (3 papers, 2016 to 2020). "RNA-seq analysis confirmed that PLK2 was up-regulated in diabetes-induced DKD rats (n = 6) compared with normal rats (n = 6)." (PMID 28655909, 2017). "We identified 338 genes altered in diabetes-induced DKD glomeruli, and PLK2 exhibited the most dramatic change." (PMID 28655909, 2017).
lung carcinoma (3 papers, 2020 to 2021). "In lung squamous cell carcinoma, PLK2/3/4 methylation was dramatically associated with longer survival time of lung cancer, whereas PLK1 methylation was significantly associated with shorter survival time." (PMID 34080290, 2021). "We analysed differential expression pattern by Oncomine, TCGA and HPA, which demonstrated that the mRNA and protein level of PLK2 were lower in lung cancer than that in normal sample." (PMID 34080290, 2021). "The staining of PLK2 protein was found high in both subtypes of lung cancer with a low level in normal tissue." (PMID 34080290, 2021). "In this study, we performed an analysis of transcriptional and protein expression to identify overexpressed PLK1/4 and under‐expressed PLK2/3 in lung cancer subtypes." (PMID 34080290, 2021). "Accordingly, we observed that the transcriptional expression of DNMTs had a positive relation with PLK1/4 and a variously negative association with PLK2/3 in lung cancer subtypes." (PMID 34080290, 2021). "PLK1 expression was higher in male than that in female patients, so was PLK4 expression between genders, whereas PLK2 presented no differential expression between male and female of lung cancer patients." (PMID 34080290, 2021). "In contrast to PLK1 expression, PLK2/3 showed an under‐expression in lung cancer compared to normal sample." (PMID 34080290, 2021).
melanoma (3 papers, 2011 to 2019). A malignant, usually aggressive tumor composed of atypical, neoplastic melanocytes. "Furthermore, WP760 downregulated IGF1R and upregulated PLK2 expression in most of the tested melanoma cell lines." (PMID 28417283, 2017). "With regard to the genes specifically up-regulated in the MCSP CTC fraction, the majority have been involved in metastasis (LOXL4, ST6GALNAC2, PYGL), tumour growth (PLK2, CYSTM1, GLUL), and/or melanoma biology (SEC31A, WIPI1, SKP1)." (PMID 30769764, 2019). "They demonstrated expression of HDAC4, MTOR, PLK2, and ABCC1 to be affected in all melanoma cell lines tested." (PMID 28417283, 2017). "The expression of four selected genes (MTOR, ABCC1, PLK2 and HDAC4) was validated in nine melanoma cell lines by qPCR." (PMID 28417283, 2017).
neuroblastoma (3 papers, 2014 to 2022). Neuroblastoma (NB) is the most common solid, extracranial childhood tumor. "Orphan nuclear receptor estrogen-related receptor gamma (ERR-gamma) induces GSK3β phosphorylation by upregulating PLK2 responsible for the differentiation of neuroblastoma SH-SY5Y cells." (PMID 29497051, 2018). "A proteome-derived peptide library obtained by digestion of undifferentiated human neuroblastoma cell line was exhaustively dephosphorylated by lambda phosphatase followed by incubation with or without PLK2 recombinant kinase." (PMID 25338102, 2014).
pulmonary fibrosis (3 papers, 2021 to 2025). Chronic progressive interstitial lung disorder characterized by the replacement of the lung tissue by connective tissue, leading to progressive dyspnea, respiratory failure, or right heart failure. "The objective of the present study was to examine PLK2 gene expression in different entities of human pulmonary fibrosis and to characterize the pulmonary phenotype of PLK2 deficient mice." (PMID 33799608, 2021). "Our results prompt further investigation of PLK2 function in pulmonary fibrosis and suggest that the PLK2 KO model displays a genetic predisposition towards pulmonary fibrosis, which could be leveraged in future research on this topic." (PMID 33799608, 2021). "With a genetic predisposition towards pulmonary fibrosis and early stage pro-fibrotic alterations of the alveolar histoarchitecture, the PLK2 KO model could be used in further research on this topic." (PMID 33799608, 2021). "The present study identified a potential role of PLK2 in the pathophysiology of human pulmonary fibrosis." (PMID 33799608, 2021). "We found a significant downregulation of PLK2 in four different entities of human pulmonary fibrosis." (PMID 33799608, 2021). "However, the function of PLK2 in pulmonary fibrosis development remains unclear." (PMID 33799608, 2021).
B-cell neoplasm (2 papers, 2017 to 2020). A group of heterogeneous lymphoid tumors generally expressing one or more B-cell antigens or representing malignant transformations of B-lymphocytes. "Significantly lower expression of Plk2 has been observed in a wide range of B-cell neoplasms due to CpG methylation that causes transcriptional silencing of Plk2, supporting the role of Plk2 as a tumor suppressor in hematopoietic diseases." (PMID 27902479, 2017). "In a wide range of B-cell neoplasms, PLK2 was epigenetically silenced due to the aberrant CpG methylation." (PMID 33176854, 2020).
cholangiocarcinoma (2 papers, 2021). A carcinoma that arises from the intrahepatic biliary tree (intrahepatic cholangiocarcinoma) or from the junction, or adjacent to the junction, of the right and left hepatic ducts (hilar cholangiocarcinoma). "In cholangiocarcinoma, pharmacological inhibition of PLK2 via BI6727 and PLK2 knockdown degrade the anti-apoptotic protein myeloid cell leukemia 1 (Mcl-1) which represents a survival factor in this malignancy, and lead to apoptosis and tumor suppression in vivo." (PMID 34065956, 2021).
colon carcinoma (2 papers, 2007 to 2021). "It has been reported that PLK2 can phosphorylate Ser-137 of PLK1 to promote human colon cancer cell survival in cells with mitochondrial dysfunction." (PMID 35156101, 2021).
colorectal tumor (2 papers, 2022 to 2025). "Degradation of FBXW7 by Plk2 increases Cyclin E levels, promoting cell proliferation, inhibiting apoptosis, and enhancing colorectal tumor growth." (PMID 41373479, 2025).
dementia (2 papers, 2016 to 2022). Loss of intellectual abilities interfering with an individual's social and occupational functions. "PLK2 plays a critical role in the phosphorylation of α-synuclein in the central nervous system, a modification that leads to the formation of pathologic aggregates (Lewy bodies) and, consequently, neurotoxicity, as in the case of PD and dementia." (PMID 35270118, 2022).
diabetic kidney disease (2 papers, 2022 to 2025). Progressive kidney disorder caused by vascular damage to the glomerular capillaries, in patients with diabetes mellitus. "Plk2 attenuates diabetic kidney disease (DKD)-induced ROS production and mitochondrial membrane potential (MMP) induction and regulates podocyte apoptosis and inflammation." (PMID 35300109, 2022). "Additionally, PLK2 promotes renal fibrosis in diabetic nephropathy via Notch signaling activation." (PMID 41019094, 2025).
pancreatic cancer (2 papers, 2022 to 2023). "However, in colorectal, bladder, and pancreatic cancer, Plk2 was reported as an oncogenic factor because of its overexpression and tumor-promoting effects." (PMID 35842499, 2023). "We investigated the effect of PLK1 inhibition on pancreatic cancer cells using NMS-P937, a selective PLK1 inhibitor (PLK1i), which has 5000-fold higher selectivity than PLK2/PLK352." (PMID 35773310, 2022).
renal fibrosis (2 papers, 2025). A final common manifestation of a wide variety of chronic kidney diseases characterized by glomerulosclerosis and tubulointerstitial fibrosis. "Silencing PLK2 significantly inhibited the activation of the Notch1 signaling pathway and reduced the expression of renal fibrosis-related markers, while overexpression of HES1 rescued the downregulation of markers induced by si-PLK2." (PMID 40822939, 2025).
small cell lung carcinoma (2 papers, 2021). Small cell lung cancer (SCLC) is a highly aggressive malignant neoplasm, accounting for 10-15% of lung cancer cases, characterized byrapid growth, and early metastasis. "In Bhattacharjee Lung Statistics, PLK2 was found to be lower expressed in small cell lung carcinoma (fold change = −5.625) and lung carcinoid tumour (fold change = −7.189) versus normal sample." (PMID 34080290, 2021). "On the other hand, PLK2 expression was also correlated with improved cell survival using knockdown techniques in head and neck cancer and non–small cell lung cancer cell lines." (PMID 35156101, 2021).
viral infection (2 papers, 2022). "However, the role of PLK2 in immunity to viral infection has been studied far less than that of other family members." (PMID 35898867, 2022). "Contrasting to its family members, PLK2 is poorly studied in viral infection, and the exact role and mechanism remain unclear." (PMID 35898867, 2022).
acute kidney injury (1 paper, 2023). Sudden and sustained deterioration of the kidney function characterized by decreased glomerular filtration rate, increased serum creatinine or oliguria. "However, the roles of Plk2 in acute kidney injury (AKI) have not been clarified." (PMID 35842499, 2023).
androgen excess (1 paper, 2025). "To validate the critical role of PLK2 in PCOS pathogenesis, we established a DHEA-induced hyperandrogenic rat model (n = 6) to recapitulate androgen excess and ovarian dysfunction characteristic of PCOS." (PMID 41019094, 2025).
bladder transitional cell carcinoma (1 paper, 2022). The most common morphologic subtype of urinary bladder carcinoma (over 90% of cases). "The overexpressed PLK2 was detected in BC, and urinary PLK2 protein level was highly correlated with bladder transitional cell carcinoma." (PMID 36033441, 2022).
breast tumors (1 paper, 2021). "Patients with primary breast tumors had lower expression of PLK2 mRNA, but higher levels of PLK1 mRNA, relative to normal breast tissue." (PMID 35156101, 2021).
Cognitive impairment (1 paper, 2019). Abnormal cognition is characterized by deficits in thinking, reasoning, or remembering. "It is interesting to note that both Aβ and Plk2 cause synapse loss, a process which is strongly associated with cognitive impairment in AD, while pharmacological inhibition of Plk2 function ameliorates synapse loss and memory decline in an aggressive mouse model of AD." (PMID 31306446, 2019).
endothelial dysfunction (1 paper, 2025). In vascular diseases, endothelial dysfunction is a systemic pathological state of the endothelium (the inner lining of blood vessels) and can be broadly defined as an imbalance between vasodilating and vasoconstricting substances produced by (or acting on) the endothelium. "Our study systematically elucidates the pivotal role of endothelial cells in the glycolytic reprogramming associated with PCOS, and identifies PLK2 as a key regulatory factor linking endothelial dysfunction, enhanced glycolysis, and immune imbalance." (PMID 41019094, 2025). "The interplay between endothelial dysfunction, glycolytic reprogramming, immune imbalance, and PLK2 provides a comprehensive perspective on PCOS pathogenesis." (PMID 41019094, 2025).
escherichia coli infection (1 paper, 2017). Infection with the organism Escherichia Coli.
imbalance (1 paper, 2025). "Our study extends this concept by proposing PLK2 as a key mediator linking endothelial glycolytic dysregulation and immune imbalance in PCOS." (PMID 41019094, 2025).
injury (1 paper, 2023). Damage inflicted on the body as the direct or indirect result of an external force, with or without disruption of structural continuity. "By analysis of the published data from the ischemic AKI model developed with unilateral renal ischemia–reperfusion injury (GSE192883), the relative gene expression of Nfe2l2, Plk2, and Cdkn1a was upregulated." (PMID 35842499, 2023).
keloid (1 paper, 2026). An irregularly shaped, elevated mark on the skin caused by deposits of excessive amounts of collagen during wound healing. "Histological and protein-level assays demonstrated significantly higher expression of ADRB2 and PLK2 in keloid tissues compared with adjacent normal skin." (PMID 41737208, 2026). "In keloid fibroblasts, fibrotic markers (COL1/COL3) and autophagy-related markers (LC3-II/LC3-I and p62) were upregulated concomitantly with ADRB2 and PLK2 at baseline." (PMID 41737208, 2026).
kidney injuries (1 paper, 2017). "NAC, an antioxidant reagent, rescued HDG and PLK2 overexpression-induced kidney injuries." (PMID 28655909, 2017).
knee osteoarthritis (1 paper, 2022). "In addition, animal experiments in rats with knee osteoarthritis showed that upregulation of miR-27a inhibited cartilage collagen destruction and synovial angiogenesis by inhibiting polo-like kinase 2 (PLK2)." (PMID 36346531, 2022).
Lewy body disease (1 paper, 2021). "We chose the PLK2 family member because several independent reports suggest that PLK2 is a major synuclein kinase in vitro and in mouse, rat, and human Lewy body disease brain." (PMID 33428941, 2021). "Although a substantial body of literature suggests that PLK2 is an important alpha-synuclein kinase, potentially relevant in nonhuman primate and human Lewy body disease tissue, genetic deletion of PLK2 in mice does not completely abolish endogenous mouse serine-129 phosphorylation." (PMID 33428941, 2021).
lung adenocarcinoma (1 paper, 2021). A carcinoma that arises from the lung and is characterized by the presence of malignant glandular epithelial cells. "Higher methylation level of PLK1/3 promoter was associated with poor survival probability of patients with lung adenocarcinoma, while higher methylation level of PLK2/4 was significantly related to favourable survival probability of patients with lung adenocarcinoma." (PMID 34080290, 2021). "PLK2 expression was lower in lung adenocarcinoma (P < .05), and PLK3 was also under‐expressed in lung adenocarcinoma (P < .001)." (PMID 34080290, 2021). "In accordance with methylation level and the correlation with DNMTs, PLK2 expression was not intervened by methylation in lung adenocarcinoma or lung squamous cell carcinoma." (PMID 34080290, 2021).
lung squamous cell carcinoma (1 paper, 2021). "The methylation of PLK1/3/4 genes kept a higher level in lung squamous cell carcinoma sample than that in normal lung sample; however, PLK2 methylation stayed at lower level in lung squamous cell carcinoma than normal tissue." (PMID 34080290, 2021). "The data from PLK2 expression revealed a slight decline in primary lung squamous cell carcinoma (P = .146)." (PMID 34080290, 2021). "In lung squamous cell carcinoma, PLK1/3/4 promoters presented a higher methylation in primary tumour, whereas PLK2 promoter methylation was at lower level in primary tumour than that in normal sample." (PMID 34080290, 2021). "While in lung squamous cell carcinoma, the methylation was strengthened in PLK1/3/4 genes while weakened in PLK2 gene." (PMID 34080290, 2021). "In lung squamous cell carcinoma, DNMT1 expression was negatively related with PLK2 level." (PMID 34080290, 2021).
memory impairment (1 paper, 2019). "Furthermore, pharmacological inhibition of Plk2 also reduced Aβ production, synapse loss, and memory impairments in the AD model mice." (PMID 31306446, 2019). "Thus, we conclude that Plk2 contributes substantially to localized amyloid plaque formation and mediates physiological activity-dependent amyloidogenic APP processing in the brain, and that suppressing this pathway can functionally rescue disease-relevant synaptic pathology and memory impairment." (PMID 31306446, 2019).
oral lichen planus (1 paper, 2019). Oral lichen planus is a chronic inflammatory oral condition of unknown aetiology characterized by T-cell-mediated chronic immune response and abnormal epithelial keratinization cycle. "In contrast, down-regulated miR-27b in oral lichen planus promotes human oral keratinocytes proliferation via increased Polo-like Kinase-2 expression." (PMID 31930115, 2019).
ovarian dysfunction (1 paper, 2025). The inability of the ovaries to function. "The high-PLK2 subgroup exhibited significantly increased neutrophil infiltration, consistent with prior studies implicating neutrophil-driven inflammation in oxidative stress and ovarian dysfunction." (PMID 41019094, 2025).
ovarian tumor (1 paper, 2022). "Using in vivo models where a tumor xenograft mouse model was established, we found that anlotinib significantly suppressed the growth of cisplatin-resistant ovarian tumors compared to that observed in the control group by increasing the expression level of PLK2." (PMID 36558006, 2022).
sarcoidosis (1 paper, 2025). Sarcoidosis is a multisystemic disorder of unknown cause characterized by the formation of immune granulomas in involved organs. "We found that serine/threonine-protein kinase PLK2 (Q9NYY3) protein level in plasma EVs was highly correlated with the occurrence of lung fibrosis in sarcoidosis." (PMID 41279897, 2025).